YY1 (YY1 transcription factor)
Diseases named in the same sentence as YY1 in open-access papers (continued):
Sharing a sentence is not in itself a finding about the gene and the disease.
cholangiocarcinoma (continued). "In addition, the same study showed that only cholangiocarcinoma, DLBC, and KIRP cases with genetic alteration had copy number deletion of YY1, while the “amplification” type of CNVs was only seen in adrenocortical carcinoma and pheochromocytoma/paraganglioma tumors." (PMID 37894300, 2023).
bladder cancer (19 papers, 2019 to 2025). "First, the result of Pearson correlation analysis indicated that the expression of CRTAC1 was negatively associated with YY1 in the tissues of bladder cancer patients." (PMID 34818994, 2021). "Additionally, YY1 has been documented to be overexpressed in bladder cancer tissues and high-grade cells, and its expression is associated with disease-free survival in bladder cancer patients." (PMID 34818994, 2021). "Similar to this, H3K18la upregulates the transcription factors Y-box binding protein 1 (YBX1) and Yin Yang 1 (YY1) in bladder cancer, promoting anlotinib resistance and ultimately cisplatin resistance." (PMID 41267990, 2025). "In bladder cancer, H3K18la upregulates the expression of the transcription factor Yin Yang 1 (YY1) and the Y-box binding protein 1 (YBX1), promoting resistance to cisplatin." (PMID 40057816, 2025). "MiR-138-5p plays a critical role in the suppression of bladder cancer by inhibiting the expression of oncogenic YY1 factor, thereby reducing YY1-driven proliferation of cancer cells." (PMID 39936993, 2025). "Activation of transcription factors YBX1 and YY1 enhances cisplatin resistance in bladder cancer cells." (PMID 41179284, 2025). "Overall, CRTAC1 inhibits cell proliferation, migration, invasion and EMT process in bladder cancer by downregulating YY1 to inactivate the TGF-β pathway." (PMID 34818994, 2021). "Rescue assays were performed to explore the effect of YY1 on malignant behaviors of bladder cancer cells after CRTAC1 overexpression." (PMID 34818994, 2021). "YY1 has been reported to activate the TGF-β signaling in bladder cancer and mediate the EMT pathway." (PMID 34818994, 2021). "YY1 overexpression reverses the suppressive effect of CRTAC1 overexpression on malignant behaviors of bladder cancer cells." (PMID 34818994, 2021). "Overall, CRTAC1 inhibited malignant phenotypes of bladder cancer cells by targeting YY1 to inactivate the TGF-β pathway." (PMID 34818994, 2021). "According to Immunofluorescent staining and Co-IP assays, colocalization of CRTAC1 and YY1 was identified in the nucleus of bladder cancer cells." (PMID 34818994, 2021). "Then, the expression and colocalization of CRTAC1 and YY1 in the nucleus of bladder cancer cells was visualized by immunofluorescent staining assay." (PMID 34818994, 2021). "YY1 regulates epithelial-mesenchymal transition (EMT) markers in bladder cancer by activating the TGFβ pathway." (PMID 34818994, 2021). "CRTAC1 overexpression decreased the mRNA and protein levels of YY1, while CRTAC1 deficiency showed opposite effects on YY1 expression, which indicated that CRTAC1 negatively regulated YY1 expression in bladder cancer cells." (PMID 34818994, 2021). "In summary, CRTAC1 inhibits cell proliferation, migration, invasion and EMT process in bladder cancer by downregulating YY1 to inactivate the TGF-β pathway." (PMID 34818994, 2021). "The expression of CRTAC1 and YY1 was negatively correlated with each other in the tissue samples of bladder cancer." (PMID 34818994, 2021). "In the present study, we demonstrated that YY1 activated the TGF-β signaling while CRTAC1 inhibited the activation of TGF-β signaling by targeting YY1 in bladder cancer cells." (PMID 34818994, 2021). "Rescue assays indicated that CRTAC1 inhibited malignant behaviors of bladder cancer cells by targeting YY1." (PMID 34818994, 2021). "YY1 overexpression has been reported in various malignancies, including both pediatric and adult cancers, such as hepatocellular carcinoma, prostate cancer, bladder cancer, and BC." (PMID 41009346, 2025). "Moreover, miR-192-5p has been reported to inhibit the growth of bladder cancer cells by targeting YY1." (PMID 38254634, 2023). "The reported study revealed that YY1 inhibits the EMT process in bladder cancer cells by reducing expression levels, regulating the TGF‐β pathway, and maybe a potential therapeutic target for future bladder cancer." (PMID 34541834, 2022).
bladder cancer (continued). "Mechanistically, CRTAC1 directly targets YY1 in bladder cancer cells." (PMID 34818994, 2021). "Mechanistically, CRTAC1 targeted YY1 in bladder cancer cells." (PMID 34818994, 2021). "Additionally, mRNA and protein expression of YY1 was decreased by CRTAC1 overexpression and increased by CRTAC1 knockdown, which indicated that CRTAC1 negatively regulated YY1 expression in bladder cancer cells." (PMID 34818994, 2021). "Then, we measured the expression of YY1 in bladder cancer tissue samples." (PMID 34818994, 2021). "The result indicated that YY1 was highly expressed in bladder cancer tissues." (PMID 34818994, 2021). "CRTAC1 negatively modulated the mRNA and protein expression of YY1 in bladder cancer cells." (PMID 34818994, 2021). "Moreover, rescue experiments implied that CRTAC1 inhibits malignant behaviors of bladder cancer cells by downregulating YY1." (PMID 34818994, 2021). "The mRNA and protein levels of YY1 were upregulated in bladder cancer cells." (PMID 34818994, 2021). "Moreover, YY1 was expressed at a high level in bladder cancer tissues." (PMID 34818994, 2021). "In cisplatin-resistant bladder cancer cells, H3K18la upregulates YBX1 and YY1 expression to confer cisplatin resistance." (PMID 41310104, 2025). "They demonstrated that the H3 K18 la in the promoter regions activates the transcription factors Y-box binding protein 1 (YBX1) and Yin Yang 1 (YY1), which induce DDP resistance in bladder cancer." (PMID 40264038, 2025). "YY1 overexpression was revealed to reverse the inhibitory effect of upregulated CRTAC1 on TGF-β signaling and bladder cancer cell viability, proliferation, migration, invasion and EMT process." (PMID 34818994, 2021). "Moreover, we explored whether CRTAC1 regulated YY1 level in bladder cancer cells." (PMID 34818994, 2021). "In conclusion, CRTAC1 inhibits bladder cancer cell proliferation, migration, invasion and EMT by targeting YY1 to inactivate the TGF-β signaling pathway." (PMID 34818994, 2021). "Polycomb protein, Yin Yang 1 (YY1), mediates the interaction between uc.8 and miR-596 through protein-RNA binding, providing an additional layer of regulation in bladder cancer cells." (PMID 31167408, 2019).
insulinomas (19 papers, 2017 to 2025). "Epigenetic profiling has identified unique subtypes, including insulinomas harboring YY1 mutations, suggesting novel druggable dependencies." (PMID 40429384, 2025). "These typical insulinomas become symptomatic very early when they are small in size (< 2 cm) and are characterized by somatic YY1 mutations in about 30% of cases, or recurrent somatic amplifications (in particular chromosome 7 amplifications)." (PMID 37152923, 2023). "Mutation of the third zinc finger region of YY1 has been shown to alter its transcriptional activity, which promotes tumorigenesis in insulinoma." (PMID 36835815, 2023). "We found that a YY1 mutation is specific for insulinomas and has a role in driving the degree of malignancy." (PMID 33985581, 2021). "Another genetic link between diabetes and insulinoma was suggested by the presence of a recurrent somatic T372R mutation in YY1 (Yin and Yang 1 protein) in 30% of tumors." (PMID 33101198, 2020). "YY1 was shown to be recurrently mutated in insulinomas, while mutations in ATRX/DAXX/MEN1 are very uncommon." (PMID 32512761, 2020). "In addition, 30% of insulinoma patients have mutations in the YY1 gene, which regulates the transcription of CXCL12 with antidiabetic potential." (PMID 38334891, 2024). "The YY1 gene mutation was frequent only in copy-neutral insulinomas (Ins-Neutral)." (PMID 39456803, 2024). "It is assumed that mutations in YY1 gene are driver mutations for insulinomas." (PMID 34737724, 2021). "However, the most common mutation in insulinoma is a gain of function mutation Trp372Arg in YY1 gene that occurs in 30% in Asian population and in 13% in Caucasian (German) population." (PMID 34737724, 2021). "However, the YY1 p.T372R mutation can be used as an effective target for screening insulinoma patients and predicting prognosis." (PMID 33985581, 2021). "Similar to its localization in PDAC cells, YY1 is localized mainly in the nucleus in insulinoma cells; however, YY1 is more highly expressed in malignant insulinoma than in PDAC and often indicates a worse prognosis." (PMID 33985581, 2021). "For example, the higher the levels of YY1 expression are, the higher is the malignant potential of insulinoma." (PMID 33985581, 2021). "The predominant recurring genetic variant in up to 30% of sporadic insulinomas is an activating T372R missense mutation in the Yin Yang 1 (YY1) gene, which is absent in NF-PanNET." (PMID 39954168, 2025). "YY1-related diseases include insulinoma and Gabriele-De Vries Syndrome." (PMID 39129166, 2025). "Insulinomas, NETs that produce insulin and are predominantly found in the pancreas, frequently exhibit mutations in the transcription factor YY1, which is absent in nonfunctioning pancreatic NETs." (PMID 40026252, 2025). "In a study using whole-exome gene sequencing to compare the genomic profiles of 84 insulinomas with 127 non-functioning pNETs (NF-pNETs), Yin Yang 1 (YY1) mutations were unique to a minority of insulinomas (25%) and not noted in any NF-pNETs." (PMID 36835815, 2023). "In addition, the expression intensity of YY1 in malignant insulinoma and benign insulinoma is significantly different, and the expression intensity of YY1 and the benign and malignant properties of insulinoma are positively correlated." (PMID 33985581, 2021). "YY1 mutations do not occur in non-functioning NETs, but a somatic gain-of-function T372R substitution is found in approximately one-third of insulinomas, resulting in an adenylyl cyclase and calcium channel increased expression and the subsequent dysregulation of insulin secretion." (PMID 39456803, 2024).
diabetes (17 papers, 2018 to 2025). "YY-1 has been shown to act in numerous processes the disturbance of which is associated with the development of diabetes and its complications as well as the regulation of systemic inflammation." (PMID 39273245, 2024). "We hypothesized that YY1 mediates diabetes-associated cardiac fibrosis." (PMID 41170186, 2025). "Diabetes-induced cardiac hypertrophy and HF are chronic processes; therefore, it is reasonable that YY1 functions as a hypertrophic factor under these conditions." (PMID 39850120, 2025). "Among them, Foxo1, Myc, Yy1, and Cebpa were reported in literature to be essential TFs in regulating diabetes." (PMID 29995913, 2018). "We found that HG or diabetes enhanced STAT3 binding to YY1, which DAPA suppressed." (PMID 41170186, 2025). "However, YY1 is also a transcription factor that restores pancreatic β cell function and inhibits the onset of diabetes." (PMID 33985581, 2021). "YY1 can reduce the incidence of diabetes by regulating the transcription of the CXCL12 gene." (PMID 33985581, 2021). "However, some studies have shown that YY1 is closely related to the pathogenesis of diabetes." (PMID 33985581, 2021). "In addition, a study by Klöting confirmed that the YY1 gene is a protective gene for rat diabetes." (PMID 33985581, 2021). "Studies have also shown that inactivation of YY1 impairs mitochondrial OXPHOS activity in mouse models and induces mitochondrial dysfunction and diabetes." (PMID 41334450, 2025). "In diabetic db/db mice, administration of DAPA remarkably ameliorated diabetes-induced STAT3 activation, YY1 nuclear translocation, CF proliferation and activation, and reduced cardiac fibrosis and dysfunction." (PMID 41170186, 2025). "In recent years, extensive research has been conducted to investigate the role of YY1 in various biological processes, including skeletal muscle differentiation, autophagy, tumor proliferation, VSMC proliferation, and diabetes, among others." (PMID 39519329, 2024). "While our data suggests a putative crosstalk between YY1/SRF-related mechanisms and OGT-mediated VSMC de-differentiation, additional studies are warranted to elucidate the molecular pathways that link OGT to YY1 and SRF in regulation of VSMC phenotypic transformation in diabetes." (PMID 37175604, 2023). "Our current findings prompt us to speculate that YY1- and SRF-dependent pathways play a regulatory role in OGT-mediated SMC de-differentiation induced by hyperglycemia, promoting accelerated atherosclerotic lesion formation in diabetes." (PMID 37175604, 2023).
multiple myeloma (16 papers, 2013 to 2025). "Moreover, we found that YY1 mutation could affect the expression changes of certain genes in some cancers; for example, in multiple myeloma, YY1 mutation could affect the expressions of ERMN, DUSP8, PRG2, BMF, and RNASE2 genes." (PMID 35791393, 2022). "In multiple myeloma, YY1 promotes AKR1C3 expression and activates hedgehog signaling to promote glycolytic activity and lenalidomide resistance." (PMID 40867514, 2025). "The results showed that KLF6, NR3C1, IRF7 and YY1 were all actively regulated in C0 IGLC3+ Myeloma Cells, C1 IGHA1+ Myeloma Cells, and JUN was actively regulated in C0 IGLC3+Myeloma Cells, C1 IGHA1+ Myeloma Cells and C3 IGHG4+ Myeloma Cells." (PMID 40406148, 2025). "Owing to the pro-apoptotic function of Bim, its repression by the YY1-RelA complex has been shown to play an important role in the survival of multiple myeloma cells." (PMID 31824839, 2019). "Multiple myeloma cells also show enhanced NFκB activity, and the NFκB target gene YY-1 is often hyperexpressed resulting in transcriptional repression of Bim transcription." (PMID 26405162, 2015). "In line with this, depletion of either YY1 or RelA severely impaired MM tumor growth in xenograft models for human Myeloma in nude mice." (PMID 23874387, 2013). "While hyperexpression of YY1 and its role in different types of malignancies has been reported, its role in Multiple Myeloma has remained elusive." (PMID 23874387, 2013). "In addition, previous studies have reported that MYC negatively regulates the expression of miR-34a-5p in multiple myeloma, and YY1 levels are inversely related to miR-155 in atherogenesis." (PMID 36212136, 2022). "In addition to lymphoma and myeloma, YY1 has also been shown to play an important role in promoting acute myeloid leukemia (AML)." (PMID 31824839, 2019). "YY1-RelA complex represses the pro-apoptotic gene Bim in multiple myeloma cells." (PMID 31824839, 2019). "A comprehensive study has been reported investigating the role of the NF-κB/Snail/YY1/RKIP circuitry in multiple myeloma and how each gene is correlated with the remaining genes in this axis by examining various myeloma-related Gene Expression Omnibus (GEO) datasets." (PMID 28476134, 2017). "In multiple myeloma, Bim transcription is repressed by the Yin Yang 1 (YY1)-RelA (p65) complex." (PMID 26405162, 2015). "Moreover, depletion of either YY1 or RelA completely inhibited MM tumor growth in xenograft models for human myeloma." (PMID 23874387, 2013). "Next, we further analyzed the regulatory activity of TOP5 TF of C0 IGLC3+ Myeloma cells, and we visualized the expression of KLF6, NR3C1, IRF7, YY1 and JUN in all cells and different tissue sources." (PMID 40406148, 2025). "YY1 upregulates AKR1C3 and the hedgehog axis to enhance lenalidomide (LEN) resistance in multiple myeloma cells." (PMID 40867514, 2025). "In multiple myeloma, METTL3 increases YY1 expression and promotes tumor progression by enhancing the RNA stability of YY1." (PMID 37996892, 2023). "In human myeloma cells, Ikaros zinc finger 1 (IKZF1) was identified as the pivotal transcriptional activator of SLAMF7; however, the murine SLAMF7 (mSLAMF7) promoter was found to be regulated by YY1 in B cells." (PMID 40247106, 2025).
acute myeloid leukemia (15 papers, 2009 to 2025). Acute myeloid leukemia (AML) is a group of neoplasms arising from precursor cells committed to the myeloid cell-line differentiation. "Consistently, YY1 enhances METTL3 expression as a transcription factor in the human acute myeloid leukemia cell lines Kasumi-1 and THP-1." (PMID 39800682, 2025). "Another axis, the stromal cell-derived factor-1 (SDF-1a)/cxc motif chemokine receptor 4 (CXCR4), has been found to increase YY1 in acute myeloid leukemia (AML) cells." (PMID 37686541, 2023). "YY1 overexpression has previously been observed in different types of cancers, such as breast, prostate, ovarian, colon, melanoma, and acute myeloid leukemia." (PMID 35408813, 2022). "In acute myeloid leukemia, YY1 negatively regulates let-7a, which inhibits the expression of the anti-apoptotic protein B-cell lymphoma-extra-large (BCL-xL); instead, miR-7 may silence YY1 and KLF4 mRNAs, contributing to chemoresistance." (PMID 38339244, 2024). "TF Yin-Yang 1 (YY1) is a new target for treating acute myeloid leukemia." (PMID 38481812, 2024). "Finally, Snhg5 upregulation induced by YY1 contributes to angiogenesis in acute myelogenous leukemia." (PMID 38110334, 2023). "In acute myeloid leukemia (AML) cells, YY1 was revealed to bind and interact with HDAC1/3." (PMID 38539569, 2024). "Treatment with an HDAC inhibitor treatment significantly reduces the binding of YY1 to HDAC 1/3, resulting in an excessive LLPS state, thereby reducing the expression of METTL3 and the proliferation of acute myeloid leukemia cells." (PMID 38481812, 2024). "As opposed to the direct ways YY1 can drive neovascularization, studies on acute myelogenous leukemia (AML) have highlighted indirect methods as well." (PMID 41327312, 2025).